IL12B (interleukin 12B)
Diseases named in the same sentence as IL12B in open-access papers (continued):
Sharing a sentence is not in itself a finding about the gene and the disease.
colorectal cancer (1 paper, 2020). A primary or metastatic malignant neoplasm that affects the colon or rectum. "The expression of IL-12B) were associated with the risk of developing colorectal cancer (CRC)." (PMID 32149085, 2020). "Furthermore, the mRNA levels of IL-12B) were associated with the risk of developing colorectal cancer (CRC)." (PMID 32149085, 2020).
complication (1 paper, 2024). Any disease or disorder that occurs during the course of, or because of, another disease, treatment, or procedure. "Our findings demonstrated that genetically predicted higher levels of IL-12B and LIF likely increased the risk of T1D with renal complications, whereas higher levels of ARTN, CCL28, and S100A12 were related to a decreased risk." (PMID 39040677, 2024).
coronary artery disease (1 paper, 2022). "Lower circulating levels of IL-12B may be reflective of disrupted immunity and impaired antitumor activity, as has earlier been demonstrated for smoking patients with coronary artery disease." (PMID 35745254, 2022).
cutaneous sarcoidosis (1 paper, 2022). "RNA in situ hybridization in pulmonary and cutaneous sarcoidosis biopsies also confirmed significant IL12B staining in myeloid cells (histiocyte morphology) in both cutaneous and pulmonary sarcoidosis relative to controls." (PMID 35668129, 2022).
dry eye (1 paper, 2023). "Expression of NF-kB associated or mediated inflammatory factors that have been found to increase or contribute to dry eye pathogenesis, including myd88, cytokines il12a, il12b (a subunit shared by IL-23 and IL-12), ltb and chemokine ccl2, was evaluated by PCR." (PMID 37036417, 2023). "Increased expression of NF-kB regulated cytokines (il12a, il12b, and ltb) and the chemokine ccl2 that are involved in dry eye pathogenesis was also observed." (PMID 37036417, 2023).
dyslipidaemia (1 paper, 2018). "Therefore, we analysed gene-gene epistatic interactions between ENHO SNPs (rs2281997, rs72735260) and Th1 cell cytokine gene SNPs (IL12A rs568408, IL12B rs3212227, and IL18 rs360719) with respect to both types of dyslipidaemia." (PMID 30413149, 2018).
enthesitis (1 paper, 2025). Inflammation at the site of insertion of ligaments, tendons, and other fibrous structures into bone. "Other key genes involved in enthesitis were up‐regulated including CSF2 (encoding granulocyte–macrophage CSF), IL12B, IL6, and notably CD80 and CD83 encoding the M1‐associated costimulatory receptors." (PMID 40320905, 2025).
eosinophilia (1 paper, 2023). "We found that the transcript levels of Il12a, Il12b, and Il23a were increased in the lungs of neutrophilia-dominant mice compared to the eosinophilia-dominant mice or the control mice." (PMID 37898756, 2023).
fibrosarcoma (1 paper, 2014). A malignant mesenchymal fibroblastic neoplasm affecting the soft tissue and bone. "qRT-PCR revealed that the levels of mRNA for the proinflammatory cytokines Ifng, Il1b, and Il12b and the anti-inflammatory cytokine Il10 in fibrosarcomas induced by 5 μg MCA were similar in WT and CD155-deficient mice in both C57BL/6N and BALB/c backgrounds." (PMID 25384044, 2014).
fungal infection (1 paper, 2021). "The absence of Gal-3, in fungal infection, a positively modulated gene involved in phagocytosis (sftpd) and negatively genes involved in signal transduction (syk and myd88), proinflammatory cytokines il-1β and il-12b and cd209a receptor." (PMID 34203011, 2021).
gout (1 paper, 2018). A condition characterized by painful swelling of the joints, which is caused by deposition of urate crystals. "A study of a Chinese cohort showed that rs3212227 (1188A/C) of the IL-12B gene was associated with gout." (PMID 30123371, 2018).
Graves disease (1 paper, 2012). Graves' disease is an autoimmune disorder that leads to overactivity of the thyroid gland (hyperthyroidism).It is caused by an abnormal immune system response that causes the thyroid gland to produce too much thyroid hormones. "Interleukin 12B (IL12B) gene polymorphisms have been linked to several inflammatory diseases, but their role in the development of Graves ophthalmopathy (GO) in Graves disease (GD) patients is unclear." (PMID 23164360, 2012).
head and neck cancer (1 paper, 2020). A primary or metastatic malignant neoplasm affecting the head and neck. "Cervical, hepatic, colorectal, gastric and head and neck cancers are the most common cancers associated with the IL12B rs3212227 SNP." (PMID 32973967, 2020).
Hepatic steatosis (1 paper, 2014). Steatosis is a term used to denote lipid accumulation within hepatocytes. "Accordingly, in the present study we have shown that both increased levels of Il12a, Il12b, Il18, Ifng, Tnfa, and Il10 mRNA expression seen in the liver of HFH fed mice and hepatic steatosis were reduced in HFL fed mice." (PMID 25251155, 2014).
hepatitis B infection (1 paper, 2013). "In HD patients, the studied IL-12 polymorphic variants seem to be associated with the anti-HBs phenotype (a) with borderline significance for IL-12A in hepatitis B vaccinated patients, and (b) significantly for IL-12B in patients who underwent natural HBV infection." (PMID 24158609, 2013).
Hyperglycemia (1 paper, 2023). An increased concentration of glucose in the blood. "M-value correlated positively with changes of IL-12B and VEGF-A during hyperglycemia (Rho ≥ 0.51)." (PMID 37400734, 2023).
hypothyroidism (1 paper, 2025). Abnormally low levels of thyroid hormone. "The inflammatory markers with the highest number of associations with hypothyroidism lead variants were IL12B (14/55), and FLT3LG (9/55), in line with previous findings." (PMID 41238958, 2025).
immune thrombocytopenia (1 paper, 2025). "This study confirms the potential relationship between circulating inflammatory proteins and immune thrombocytopenia (ITP), with four proteins (CCL4, CXCL9, IL-12B, and SCF) showing a positive association with ITP, while two proteins (IL-1α and TRANCE) exhibited a negative correlation." (PMID 40261473, 2025).
inflammatory bone diseases (1 paper, 2025). "In addition, SCSP modulates inflammatory cascades by attenuating IL-17 signaling, Toll-like receptor pathways, and key genes implicated in inflammatory bone diseases, such as Ccl2, Il17re, Fosl1, Mmp13, Ccl5, Tlr1, Il12b, and Atp6v1b1." (PMID 40926992, 2025).
inflammatory skin disease (1 paper, 2022). Inflammatory skin disorders covers a broad category that includes many conditions ranging in severity, from mild itching to grave medical health complications These disorders are common in people of all ages and races. "The relevance of ApoE, DKK1, IL12B, IL9, MANF, and VEGFC in specific inflammatory skin diseases was identified in several previous studies, as discussed further." (PMID 35393522, 2022).
intracranial aneurysms (1 paper, 2016). "Authors of a case-control study suggested that the IL-12A and IL-12B independently and jointly was involved in the susceptibility to intracranial aneurysms in a Chinese population." (PMID 26830841, 2016).
laryngeal carcinoma (1 paper, 2018). Carcinoma that arises from the laryngeal epithelium. "Increased methylation levels of promoters of TOP2A (DNA topoisomerase II alpha), PLXDC2 (plexin domain containing 2), ETNK2 (ethanolamine kinase 2), GFI1 (growth factor independent 1 transcriptional repressor), and IL12B (interleukin 12B) were detected in radioresistant laryngeal cancer cells." (PMID 29439529, 2018).
leptospirosis (1 paper, 2013). A contagious bacterial infection caused by spirochetes of the genus Leptospira. "However, up-regulation of the IL-12b gene of HBMs may not further induce IFN-γ expression in CD4+ T cells during human leptospirosis, since IL-10 in HBMs was also up-regulated and the high-level of IL-10 could suppress the immune response." (PMID 24130911, 2013).
Leukocytoclastic vasculitis (1 paper, 2021). "In this study, we identified a homozygous Indel frameshift mutation at the IL12B gene in a patient with recurrent lymphadenitis and leukocytoclastic vasculitis." (PMID 34389021, 2021).
lipoma (1 paper, 2024). A benign, usually painless, well-circumscribed lipomatous tumor composed of adipose tissue. "The trans-pQTL SNP rs12634152 on chromosome 3 which significantly correlated with IL-12B mapped to the LPP (Lipoma-preferred partner) locus." (PMID 38326779, 2024).
lymphopenia (1 paper, 2021). Reduction in the number of lymphocytes. "Conversely, the lower levels of FIt3L and IL‐12B in SEVs from patients with severe disease were negatively correlated with WBC count, peak score and length of hospitalization but positively correlated with lymphopenia." (PMID 34262673, 2021).
measles (1 paper, 2021). A highly contagious viral infection caused by the measles virus. "For example, HLA class I and HLA class II genotypes and SNPs in cytokine/cytokine receptor genes (IL12B, IL12RB1, IL2, IL10) and the cell surface measles virus receptor the CD46 gene, have been reported to affect measles vaccine-induced immunity." (PMID 34683414, 2021).
Mm (1 paper, 2023). "Il12p70 protein was not produced in measurable levels by BMDMs following Mm infection though levels of il12b mRNA were increased with imatinib treatment." (PMID 37200402, 2023).
mouth ulcers (1 paper, 2023). "Second, by using Bayesian colocalization, two correlated signals with common causal variants can be estimated at specific sites, and the causative proteins of oral ulcers (BTN3A3, IL12B, BPI, FAM213A, PLXNB2, and IL22RA2) were validated." (PMID 37369724, 2023). "In conclusion, we found strong evidence supporting six novel blood proteins (BTN3A3, IL12B, BPI, FAM213A, PLXNB2, and IL22RA2) associated with mouth ulcers." (PMID 37369724, 2023). "Ultimately, we identified 6 potential risk genes (BTN3A3, IL12B, BPI, FAM213A, PLXNB2, and IL22RA2) of mouth ulcers with altered protein abundances in the blood." (PMID 37369724, 2023). "However, only six genes (BTN3A3, IL12B, BPI, FAM213A, PLXNB2, and IL22RA2) assembled the criterion (PPH4 > 75%) in the analysis of mouth ulcers, indicating a shared single variant with mouth ulcers." (PMID 37369724, 2023). "Following this analysis, the researchers identified 6 key genes, namely BTN3A3, IL12B, BPI, FAM213A, PLXNB2, and IL22RA2, which were related to the onset of mouth ulcers." (PMID 37369724, 2023).
Mycobacterium infection (1 paper, 2009). Infections with bacteria of the genus Mycobacterium. "Individuals with loss of function IL12B mutations have been found with increased susceptibility to Mycobacterium infections and knock out mice have demonstrated increased susceptibility to infection." (PMID 19557189, 2009).
neurosarcoidosis (1 paper, 2023). A sarcoidosis that involves the nervous system. "The minor alleles at three genetic variants are associated with increased risk of neurosarcoidosis: rs3775291 near TLR3 (p = 0.003; OR = 2.01), rs4921492 near IL12B (p = 0.008; OR = 1.88), while the minor allele at rs12793173 near LOC102723568 (p = 0.006; OR = 0.53) is protective." (PMID 37621457, 2023).
Obesity (1 paper, 2025). Accumulation of substantial excess body fat. "In rats with obesity induced by monosodium glutamate, an elevation of proinflammatory cytokines IL-1β and IL-12B p40 was registered, coupled with downregulation of the anti-inflammatory system, as evidenced by reduced IL-4, IL-10, and TGF-β levels." (PMID 40259921, 2025).
Pancytopenia (1 paper, 2026). An abnormal reduction in numbers of all blood cell types (red blood cells, white blood cells, and platelets). "CpG-injected WT mice receiving double treatment, show improvement in pancytopenia, hepatosplenomegaly, and liver inflammation, with reduced expression of inflammatory cytokines (Il6, Il12b, and Tnfa) compared with untreated mice." (PMID 41561071, 2026).
periodontal disease (1 paper, 2021). "Among common oral inflammatory conditions, the presence of epigenetic modifications in proinflammatory cytokines such as Fas-associated death domain protein (FADD), interleukin-12 subunit beta (IL-12B), and interleukin-4 receptor (IL-4R) has been associated with periodontal disease." (PMID 34370052, 2021).
periodontitis (1 paper, 2019). An acute or chronic inflammatory process that affects the tissues that surround and support the teeth. "Therefore, we hypothesize that there was an association between the polymorphisms in the IL12B, IL18, and MMP9 regions and the development of periodontitis." (PMID 31065235, 2019).
prediabetes (1 paper, 2019). "Furthermore, IL-33 was directly correlated with IL-12A (IL-12B was not tested) in individuals with T2D (r = 0.42; P = 0.007; n = 41) but not in those with normoglycemia or prediabetes." (PMID 31073344, 2019).
prion disease (1 paper, 2014). A transmissible disease that is caused by a protein that is able to induce abnormal folding of normal cellular proteins, leading to characteristic spongiform brain changes, which are associated with neuronal loss without an inflammatory response. "Firstly, we looked at levels of cytokines/chemokines known to be induced in prion disease (Cxcl10, Il-12b and Il-1b)." (PMID 24655482, 2014).
prostatitis (1 paper, 2025). An infectious or non-infectious inflammatory process affecting the prostate gland. "Conversely, Interleukin-12B (IL-12B) exhibited a protective effect against prostatitis (IVWIL-12B: OR = 0.909, 95% CI: 0.842–0.981, P = .014)." (PMID 40355178, 2025). "Interleukin-10 receptor A (IL-10RA), Natural Killer Cell Receptor 2B4 (CD244), and urokinase-type plasminogen activator (uPA) may contribute to the occurrence of prostatitis, while Interleukin-12B (IL-12B) appears to serve as a protective factor against it." (PMID 40355178, 2025). "Notably, other results for IL-12B (MR Egger: OR = 0.845, 95% CI: 0.755–0.945, P = .008; weighted median: OR = 0.884, 95% CI: 0.810–0.965, P = .006; weighted mode: OR = 0.887, 95% CI: 0.811–0.969, P = .015;) also indicated a negative association with the risk of prostatitis." (PMID 40355178, 2025). "The IVW analysis result for IL-12B (IVWIL-12B: OR = 0.909, 95% CI: 0.842–0.981, P = .014) demonstrated a negative correlation with the risk of prostatitis." (PMID 40355178, 2025).
pulmonary sarcoidosis (1 paper, 2022). Sarcoidosis affecting the lung parenchyma. "We indeed found that essentially all of the IL12B expression was from a similar population of IRF8+XCR1+BATF3+ cDC1s in pulmonary sarcoidosis." (PMID 35668129, 2022).
rosacea (1 paper, 2023). A chronic erythematous skin disorder that affects the face. "The expression of proinflammatory innate cytokines, including Th1 polarizing cytokines Il12b and Tnf; Th17/Th22 polarizing cytokines Il1b, Il23a, and Il6; and Il10 were significantly induced as compared with controls showing a similar expression profile as in rosacea." (PMID 36633910, 2023). "Among innate cytokines, we observed a significant increase in TNF, IL1B, IL8, IL12B, IL23A, and IL10 — but not IL36B — in rosacea skin lesions as compared with skin from healthy donors." (PMID 36633910, 2023).
schizophrenia (1 paper, 2016). A major psychotic disorder characterized by abnormalities in the perception or expression of reality. "STRING analysis highlighted first-order protein interactions among IL12RB1 and IL12B, IL1B, IL6, and IL12A, all of which have previously been associated with schizophrenia." (PMID 27746755, 2016).
sensitization (1 paper, 2014). "In addition, SNPs in or near IL-4R, JAK1, and IL12B showed modest association with allergic sensitization." (PMID 25505553, 2014).
Splenomegaly (1 paper, 2020). Abnormal increased size of the spleen. "In relation to particular symptoms, polymorphism of IL12B rs3212227 was linked to decreased risk of prematurity (OR = 0.37;95%CI,0.14–0.98;p = 0.025), while polymorphism of IL1B rs16944 was linked to reduced risk of splenomegaly (OR = 0.36;95%CI,0.14–0.98; p = 0.034) in infants with cCMV infection." (PMID 32421725, 2020).
toxoplasmosis (1 paper, 2019). A parasitic disease contracted by the ingestion or fetal transmission of toxoplasma gondii. "The contribution of each of these cell populations to the vigorous IL-12b mRNA as observed in monocytes-enriched PBMCs from chronically infected toxoplasmosis patients therefore needs to be further investigated." (PMID 31316920, 2019). "Thus, in vitro infection of monocyte-enriched PBMCs with T. gondii induced a pro-inflammatory cytokine milieu with higher il-12b gene expression in cells from chronically infected toxoplasmosis patients." (PMID 31316920, 2019).
ulcers (1 paper, 2017). "Also, in BK, the early stage ulcers had higher expression of the IL23A and IL12B genes, which together encode the components of the IL23 cytokine, that can maintain Th17 cells." (PMID 28573109, 2017).
uveitis (1 paper, 2014). An inflammatory process affecting a part of or the entire uvea. "This study shows that IL-12B gene polymorphisms are associated with two uveitis entities known as BD and VKH syndrome." (PMID 24859272, 2014). "There is abundant evidence that immune response pathways in which IL-12 p40 (encoded by IL-12B) is involved may play an important role in the pathogenesis of uveitis." (PMID 24859272, 2014). "Given the fact that these related genes (IL-12B, IL-12Rβ1 and IL-12Rβ2) play an important role in Th1 and Th17 related immune responses, we wanted to verify the potential evidence of an association of polymorphisms in these genes with uveitis." (PMID 24859272, 2014). "Our data were confined to uveitis patients with BD and VKH and further studies should be carried out to investigate whether IL-12B is also involved in the pathogenesis of other uveitis entities." (PMID 24859272, 2014).
vulvar cancers (1 paper, 2021). "In a case-control study, using 76 tagSNPs from seven candidate genes (IL-10, IL-12A, IL-12B, IL-10RA, IL-10RB, IL-12RB1 and IL12RB2), genetic variants in the IL12B gene, (rs3181225, rs3181224, rs3212227) were associated with risk of cervical and vulvar cancers." (PMID 34683414, 2021). "The study observed a significantly increased risk of HPV-positive vulvar cancers associated with variant alleles in the CSF2 (rs25882 and rs27438) and IL-12B (rs2569254 and rs3181225) genes." (PMID 34683414, 2021).